MYC (MYC proto-oncogene, bHLH transcription factor)
Diseases named in the same sentence as MYC in open-access papers (continued):
Sharing a sentence is not in itself a finding about the gene and the disease.
leukemia (continued). "Because FBXW7 mutations affect the stability of NOTCH1 and MYC proteins, this model was characterized by a marked increase of leukemia initiating cells (LIC), due to a greater MYC protein concentration." (PMID 31226848, 2019). "In SPI1-METTL14-MYB/MYC axis, METTL14, is downregulated by SPI1, exerts an oncogenic role in enhancing leukemia stem/initiating cells self-renewal and repressing myeloid differentiation by regulating MYB and MYC via m6A modification." (PMID 30062093, 2018). "R-2-hydroxyglutarate(R-2HG), which accumulates in isocitrate dehydrogenase 1/2 (IDH1/2) mutant cancers, can increase global m6A via inhibiting FTO, resulting in the decrease of MYC/CEBPA mRNA stability and inhibition of leukemia proliferation." (PMID 30062093, 2018). "In an in vitro leukemia model, two BMI1 inhibitors, PTC-209 and PRT-4165, down-regulating the expression of NOTCH1, HES1, and c-MYC, were able to block the leukemic cells growth, suggesting that the BMI1 inhibitors can be good candidates against leukemia." (PMID 30574454, 2018). "The induction of BIMin the MYC- and RAS-driven leukemia is mediated by the downregulation of miR-17-92." (PMID 27095570, 2016). "Co-targeting of AKT and c-MYC has been recently shown to be a synergistic treatment strategy for leukemia therapy, since shikonin and its derivatives strongly deregulate the AKT signaling pathway and directly inhibit c-MYC activity." (PMID 26472107, 2015). "This indicates that inhibition of c-MYC with involvement of the ERK/JNK/MAPK and AKT pathways represents a general mechanism for shikonin and its derivatives in killing leukemia cells." (PMID 26472107, 2015). "Our data reveals the oncogenic effect of an Ikaros/MYCBP2/c-MYC axis in adult ALL, and suggests a mechanism by which CK2 inhibitors exert their anti-leukemia effect." (PMID 26517351, 2015). "The effect of shikonin on U937 cells was confirmed in other leukemia cell lines (Jurkat, Molt4, CCRF-CEM, and multidrug-resistant CEM/ADR5000), where shikonin also inhibited c-MYC expression and influenced phosphorylation of AKT, ERK1/2, and SAPK/JNK." (PMID 26472107, 2015). "JQ1 reduces c-MYC or FOSL1 transcription in multiple myeloma, leukemia, lymphoma and lung adenocarcinoma models." (PMID 24576043, 2014). "High expressions of NT5C3B, MYC, and CNP were also able to differentiate between the non-leukemia and MRD-positive groups, while only MYC could distinguish between MRD-negative and MRD-positive groups." (PMID 41596324, 2026). "In FTO high cancer cells, including leukemia and glioma, R-2HG inhibited cancer cell proliferation/survival and promoted cell cycle arrest and apoptosis, while reversing drug resistance by targeting the FTO/m6A/MYC/CEBPA signaling pathway." (PMID 41362736, 2026). "Additionally, targeting MYC, a key oncogene frequently upregulated in KMT2A-rearranged leukemia, offers another approach." (PMID 39682203, 2024). "Several studies have demonstrated that adaptive UPR activation mediated by common oncogenic alterations in leukemia can increase the ability of cells to cope with ER stress and restore ER homeostasis, including BCR-ABL, PML-RARα, and enhanced MYC, N-Ras, and c-Jun activity." (PMID 38475919, 2024). "Research has shown that by inhibiting IGF2BP2, CWI1-2 can regulate the expression of key targets (such as MYC, GPT2, and SLC1A5) in the glutamine metabolism pathway in an m6A-dependent manner, thereby inhibiting the development of AML and the self-renewal of leukemia stem cells." (PMID 38790013, 2024). "This is in line with published data showing that transient stabilization of MYC by inhibition of glycogen synthase kinase 3β (GSK-3β), which normally targets MYC for proteasomal degradation, sensitizes leukemia cells to chemotherapy leading to increased apoptotic cell death." (PMID 38184819, 2024).
leukemia (continued). "For example, in leukemia, METTL14 was shown to promote stemness by inducing MYC and MYB expression." (PMID 39563370, 2024). "In BBC2 and KG1 stem cell leukemia and lymphoma cells, the tumor suppressor miR-150-5p was downregulated by MYB and other factors [fibroblast growth factor receptor 1 (FGFR1) and MYC], but treatment with mebendazole showed increased antiproliferative activity and apoptosis induction." (PMID 38835346, 2024). "Although genomic SPOP mutation is rarely observed in human leukemia, our preliminary data identified SPOP as an essential gene in BETi-resistant leukemia cells; however, BRD4 and MYC were not direct substrates." (PMID 37036970, 2023). "The chemically synthesized CBP/p300 bromodomain inhibitor GNE-049 displays effective suppression of both CBP (IC50 = 1.1 nM) and p300 (IC50 = 2.3 nM), and exhibits strong efficacy in repressing the expression of oncogenes, such as MYC (EC50 = 14 nM), in leukaemia cells." (PMID 35836809, 2022). "The effect of shikonin on U937 cells was also confirmed in another leukemia cell lines (Molt4, Jurkat, multidrug-resistant CEM/ADR5000 and CCRF-CEM), where shikonin also known to prevent c-MYC expression and affected phosphorylation of SAPK/JNK, ERK1/2 and AKT." (PMID 35847041, 2022). "Likewise, targeting FTO/MYC/CEBPA signaling, R-2HG displays an intrinsic and broad anti-tumor activity in leukemia." (PMID 36035161, 2022). "Moreover, through targeting the FTO/MYC/CEBPA axis, R-2HG inhibited the proliferation of leukemia cells." (PMID 35186927, 2022). "R-2-Hydroxyglutarate (R-2HG) directly binds to the FTO (which participates in the m6A process) and inhibits its activity, thereby reducing the m6A modification and stability of c-MYC and CEBPA in the 5′-UTR and coding regions, leading to apoptosis of leukemia cells." (PMID 34858499, 2021). "Understanding the regulation of genes such as MYC and BCL2, and more broadly growth and apoptosis pathways, is key to understanding leukemic behavior and may also inform the ways in which leukemias acquire resistance." (PMID 34088716, 2021). "Combined expression of MYC and HOXA9 induced leukemia, whereas single gene transduction of either did not, indicating a synergy between MYC and HOXA9." (PMID 34310280, 2021). "BCL2 and MYC are key targets of KMT2A-AFF1 and promote leukemia survival." (PMID 34088716, 2021). "All the MYC/HOXA9- and HOXA9/MEIS1-induced leukemias were positive to a myeloid marker Mac1 but negative to lymphoid marker B220 or CD3e, indicating that both MYC/HOXA9- and HOXA9/MEIS1-combinations induced myeloid leukemia." (PMID 34310280, 2021). "The observation agrees with recent findings of the MYC and BCL2 loci in leukemia cells." (PMID 34880227, 2021). "For example, overexpression of MCL-1 in multiple hematopoietic lineages accelerated MYC-driven tumourigenesis whilst high levels of BCL-XL cooperates with deregulated MYC to lead to plasma cell malignancies and highly malignant leukaemia." (PMID 33799592, 2021). "Likewise, METTL14 also functions as an oncogene in the self-renewal of leukemia stem cells (LSCs) and AML maintenance via an m6A-meditated MYB/MYC-dependent regulatory pathway." (PMID 34272618, 2021). "In MLL fusion-mediated leukemia, MLL fusion directly activates the expression of MYC and HOXA9." (PMID 34310280, 2021). "Although HOXA9 maintained MYC expression to immortalize myeloid progenitors ex vivo, it did not induce leukemia in vivo." (PMID 34310280, 2021). "Thus, additional MYC activation mediated by MLL fusions and MEIS1 confers proliferative advantages sufficient to induce leukemia in vivo." (PMID 34310280, 2021). "MYC acts in favor of the progression and maintenance of AML by participating in promoting transcription and translation of the genes involed in cell growth, self-renewal of leukemia stem cell, and chemoresistance." (PMID 34372899, 2021).
leukemia (continued). "Other studies have shown that combined phosphorylation of γ-catenin by BCR-ABL1 and LYN kinase, both of which are essential in Ph+ B-ALL, promotes expression and transactivation of MYC oncogene, another key player of BCR-ABL1-driven leukemia initiation and propagation in B cell progenitors." (PMID 32806528, 2020). "Nevertheless, and even when not altered at the genetic level, the expression of MYC is usually disrupted in the commonest types of leukemia, where it is activated by several pathways, as well as at the post-transcriptional level." (PMID 32102485, 2020). "A combined BETi and CDK7 inhibitor treatment abolished MYC transcription by impeding RNAPII loading without affecting PVT1-mediated chromatin looping at the MYC locus in BETi-resistant leukemia cells." (PMID 32029739, 2020). "Capitalizing on the CRISPR interference technology, we identified the second intron of IncRNA, PVT1, as a unique bona fide gained enhancer that restored MYC transcription independent of BRD4 recruitment in leukemia." (PMID 32029739, 2020). "Proscillaridin A produced a more potent growth inhibition in cells expressing high levels of MYC protein, such as acute lymphoblastic T-cell (MOLT-4) and B-cell (NALM-6) leukemia while being less effective in colorectal (SW48) and lung (A549) cancer cells expressing low levels of MYC." (PMID 31196146, 2019). "This is not surprising, as human B and T cell leukemias all express MYC at high levels (p-value = 0.34)." (PMID 30111845, 2019). "Despite the challenges for in vivo administration, we reduced the disease burden in an aggressive MLL-AF9 leukemia model and decreased c-MYC levels without overt toxicity." (PMID 31217428, 2019). "These include CNVs altering MYC non-coding regulatory regions and specifically, our data implicate a region syntenic to the murine Myc enhancer cluster that has recently been reported to be essential for the maintenance of MLL–AF9-driven leukemia in mice." (PMID 29654271, 2018). "After induction with 4-Hydroxytamoxifen (4HT), MYC was activated and fish developed T-ALL leukemia." (PMID 28930163, 2017). "Our data show that MEK1 suppression via RNA interference and genomic engineering does not affect the proliferation of human leukemic cell lines in culture; similarly, MEK1 ablation does not impact the development of MYC-driven leukemia in vivo." (PMID 27741509, 2016). "Considering the important role of c-MYC in drug-resistant leukemia, we assume that shikonin's collateral sensitivity in CEM/ADR5000 cells may be also c-MYC-related." (PMID 26472107, 2015). "Although there has been controversy about the ability of MYC to induce leukemia on its own, our result clearly shows that MYC, when over-expressed, can initiate leukemia without any additional genetic change." (PMID 26606454, 2015). "This simple, unifying mechanism is also supported by the observation that highly specific inhibitors that target the acetyl binding pocket of BRD4 disrupt activation of some MLL-FP target genes such as MYC, and impair the growth of a wide range of different MLL-FP-mediated leukemias." (PMID 24213472, 2012). "In agreement with this hypothesis, several of the genes identified in our analysis have been suggested to be putative therapeutic targets in leukemia, with either preclinical or clinical trials underway (CDK4, CDK6, GSK3b, MYC, LCK, NFkB2, BCL2L1, NOTCH1)." (PMID 21356087, 2011). "In MLL-rearranged AML, leukemia stem cells (LSCs) are highly dependent on the purine biosynthesis pathway; CRISPR screens show that purine biosynthetic genes are selectively upregulated in LSCs, and MYC-driven purine metabolism maintains LSC stemness and differentiation arrest." (PMID 41295305, 2025).
leukemia (continued). "Additionally, FTO can enhance the stability of MYC and CEBPA mRNA, thereby promoting cell proliferation, and METTL14 and YTHDF2 promote the self-renewal of leukaemia stem cells (LSCs)/leukaemia initiating cells (LICs), while ALKBH5K promotes LSC proliferation and induces apoptosis." (PMID 39641872, 2024). "Moreover, whereas BRD4 inhibitors transitorily repressed MYC transcription in types of human leukemias regardless of their sensitivity, resistant cells exhibited a rapid restoration of MYC transcription." (PMID 36567628, 2023). "Finally, we performed quantitative RT PCR analyses of the central tumor and leukemia propagator as well as cell cycle regulator MYC in both cell lines, demonstrating a significant reduction in MYC mRNA after VEN treatment in RS4;11 but not SEM cells." (PMID 35778418, 2022). "In contrast, neither MYC nor its homologue MYCN could initiate leukemia within 200 days under these experimental conditions, indicating that activation of the MYC high signature alone is insufficient for leukemogenesis in vivo." (PMID 34310280, 2021). "Altogether, these findings open a novel scenario for targeting c-MYC transcription, and it would be of the highest importance to check whether such an AMBRA1 dependence could be detected in other different c-MYC-driven tumours, such as leukaemia or gliomas." (PMID 34302498, 2021). "MYC is essential not only in leukemia cell lines, but also the non-leukemia cancer models." (PMID 34088716, 2021). "Interestingly, as R-2HG is structurally close to α-KG, it competitively inhibits the activity of α-KG-dependent dioxygease, FTO, thereby increasing the overall level of m6A without affecting FTO expression and decreasing the stability of MYC and CEBPA mRNA in R-2HG-sensitive leukemia cells." (PMID 34485297, 2021). "mTORC1 signaling in leukemia cells regulates other growth and survival factors besides cyclin D3 and MCL-1; for example, knockdown or inhibition of mTORC1 in human T-ALL cells reduces expression of the oncoprotein c-MYC while increasing expression of the pro-apoptotic protein PUMA." (PMID 34408976, 2021). "To further understand how THZ1 synergized with BETi to suppress BETi-resistant leukemia, we compared the published Hi-C data collected in K562 (high IC50 for BETi) and THP1 (low IC50 for BETi), with a focus on analyzing the long-range chromatin interactions at the MYC locus." (PMID 32029739, 2020). "Moreover, most leukemia cell lines harbor an altered MYC form with a prolonged half-life, without possessing genetic mutations or chromosomal alterations." (PMID 32102485, 2020). "Exposing rag2:hMYC-ER larvae to 4HT beginning at 5 dpf caused 100% T-ALL penetrance by five weeks of age, but many cancers regressed upon 4HT withdrawal, suggesting some ‘leukemias’ were not stably transformed, but rather lymphoproliferations that relied upon very high MYC activity." (PMID 31731471, 2019). "Additionally, c-MYC generates repair errors by regulating transcriptional activation and expression of the alternative nonhomologous end-joining pathway resulting in aberrant DNA repair in Flt3-ITD leukemia." (PMID 30420889, 2018). "In addition to gene mutations that are known to be involved in leukemogenesis, such as ones in MYC and KRAS, we also identified mutations within PTPN21, TBX21, USP54, USP11, NCOR2, CSPP1 that have never before been identified in human leukemia." (PMID 26527318, 2016). "Importantly, we have not observed any leukemias in mice reconstituted with HSCs expanded ex vivo with Tat-MYC and Tat-Bcl-2 fusion proteins." (PMID 25170611, 2014). "Since T-ALL cells express high levels of MYC, which is essential for their proliferation, we hypothesize that WNK1 may contribute to the growth of T-ALL by maintaining high levels of MYC, making WNK1 a potential therapeutic target in this thymocyte-derived leukemia." (PMID 33051000, 2020).
leukemia (continued). "Although the transplanted animals in this study did not display any features of malignant transformation into leukaemia, this overexpression in AML cells together with a strong association to HOXA genes, cell cycle progression, MYC and E2F, indicate that NAP1L3 may have a role in leukemogenesis." (PMID 30046127, 2018). "Furthermore, GDC-0941 was not efficacious in vivo against MYC-overexpressing leukemias." (PMID 25956709, 2015). "Although METTL14 is not significantly expressed in leukemia, it also acts as an oncogene in AML, functioning in a MYC‐dependent manner." (PMID 39445003, 2024). "SOX4 also promoted MYC-mediated leukemogenesis in vivo, while neither MYC, BCL2, nor SOX4 alone induced leukemia within 200 days." (PMID 34310280, 2021). "Here we describe that MXD1, but not MYC or MNT, localizes to the nucleolus in a wide array of cell lines derived from different tissues (carcinoma, leukemia) as well as in embryonic stem cells." (PMID 27588501, 2016). "Overexpression of miR-17-92 blocked the induction of apoptosis upon oncogene inactivation in the MYC and RAS-driven but not in the BCR-ABL-driven ALL leukemia." (PMID 27095570, 2016). "Importantly, JUP, NT5C3B, MYC, and GATA3, PTK7, CNP, and ICOSLG differentiated both non-pathological conditions (non-leukemia and MRD-negative) from leukemia samples." (PMID 41596324, 2026). "Indeed, several of the IRF8/MEF2D direct target genes, such as MYC, HOXA9, and ZEB2, are highly expressed and essential in non-KMT2Ar leukemias and normal hematopoietic progenitors that do not express high levels of IRF8/MEF2D." (PMID 35301220, 2022). "Furthermore, enforced expression of another MLL fusion protein, MLL-AF9, and other non-MLL leukemia drivers, including AML1-ETO, MYC, and NRAS in primary HSPCs, show that the upregulation of Igf2bp3 is specific to MLL-Af4." (PMID 34321607, 2022). "Indeed, in E2a-/- leukemias c-MYC expression is stably amplified through trisomy at chromosome 15 and therefore does not require ICN for expression yet these leukemias are still dependent on Notch1 signaling." (PMID 35514954, 2022). "In addition to U937 cells, we investigated four other different leukemia cell lines (CEM/ADR5000, CCRF-CEM, Molt4 and Jurkat) to prove, whether or not inhibition of c-MYC expression is a general mechanism for shikonin in killing leukemia cells." (PMID 26472107, 2015). "Initially considered to work primarily through inhibition of BRD4 mediated MYC gene expression, the molecular mechanism is likely to be more complex than this as MYC expression cannot completely rescue the effect of the BET inhibitor JQ1 and some leukemias that express MYC are not sensitive to JQ1." (PMID 24213472, 2012). "Importantly, despite the mechanism through which NPQ-C6 circumvented IM-resistance was not explored, NPQ-C6 inhibited pYBCR-ABL1, pYSTAT5, c-MYC or PIM-1 in K562-R cells, which suggests that NPQ-coumarin conjugates might be able to circumvent resistance to TKI in BCR-ABL1+ leukemia." (PMID 30687103, 2018).